TIMD4 (T cell immunoglobulin and mucin domain containing 4)
Description:
Phosphatidylserine receptor that plays different role in immune response including phagocytosis of apoptotic cells and T-cell regulation. Involved in efferocytosis, the process by which apoptotic cells are removed by phagocytic cells by promoting the engulfment of apoptotic cells or exogenous particles. Mechanistically, acts by securing apoptotic cells to phagocytes through direct binding to phosphatidylserine present on apoptotic cells, while other engulfment receptors such as MERTK efficiently recognize apoptotic cells and mediate their ingestion. Controls T-cell activation in a bimodal fashion, decreasing the activation of naive T-cells by inducing cell cycle arrest, while increasing proliferation of activated T-cells by activating AKT1 and ERK1/2 phosphorylations and subsequent signaling pathways (By similarity). Also promotes autophagy process by suppressing NLRP3 inflammasome activity via activation of LKB1/PRKAA1 pathway in a phosphatidylserine-dependent mechanism (By similarity). (Microbial infection) Plays a positive role in exosome-mediated trafficking of HIV-1 virus and its entry into immune cells.
Synonyms: TIM4; SMUCKLER
Tractability: Small molecule: a structure with a bound ligand is known. Antibody: UniProt places it where antibodies can reach, with high confidence; UniProt predicts a signal peptide or a membrane-spanning region; its Gene Ontology location is reachable by antibodies, with medium confidence; the Human Protein Atlas places it where antibodies can reach.
Gene: Protein-coding gene on chromosome 5 (156,919,292 to 156,963,226, reverse strand). Ensembl gene ENSG00000145850.
Subcellular location: Cell membrane; Secreted, extracellular exosome
Subcellular location (Human Protein Atlas): Plasma membrane
Pathways (Reactome):
Disease: Dengue Virus Attachment and Entry
Gene Ontology:
Molecular function: phosphatidylserine binding
Biological process: apoptotic cell clearance; cytoskeletal rearrangement involved in phagocytosis, engulfment
Cellular component: plasma membrane; extracellular region
Genetic constraint (gnomAD): Loss-of-function variants: 27 observed, 35.4 expected, observed/expected ratio (o/e) 0.76, 90% interval 0.56 to 1.05. The upper end of that interval is the gene's LOEUF score, 1.05, which puts it in group 4 of 6, group 1 being the genes least tolerant of losing a copy. Missense variants: 455 observed, 463.98 expected, observed/expected ratio (o/e) 0.98, 90% interval 0.91 to 1.06. Synonymous variants: 196 observed, 173.32 expected, observed/expected ratio (o/e) 1.13, 90% interval 1.01 to 1.27.
Homologues: Orthologues: chimpanzee TIMD4 (97% identical), macaque TIMD4 (87% identical), pig TIMD4 (58% identical), rabbit TIMD4 (56% identical), dog HAVCR1 (48% identical), mouse Timd4 (47% identical), rat Timd4 (43% identical), Caenorhabditis elegans T25B2.1 (6% identical), Caenorhabditis elegans T13C5.9 (6% identical), Caenorhabditis elegans T13C5.10 (5% identical), Caenorhabditis elegans T13C5.2 (5% identical), Caenorhabditis elegans T13C5.3 (5% identical), and 4 more. Paralogues in human: HAVCR1 (26% identical), HAVCR2 (19% identical), MED7 (8% identical).
Diseases named in the same sentence as TIMD4 in open-access papers:
TIMD4 is named in the same sentence as 118 diseases in open-access papers, as found by Europe PMC text mining. Sharing a sentence is not in itself a finding about the gene and the disease. The quoted sentences say what the papers report.
ovarian carcinoma (26 papers, 2020 to 2025). A malignant neoplasm originating from the surface ovarian epithelium. "Here, we found 2 peritoneal macrophage subsets in mice bearing ID8 ovarian cancer based on T cell immunoglobulin and mucin domain containing 4 (Tim-4) expression." (PMID 32780724, 2020). "Over‐expression of TIMD4 in DLBCL cancer cells, lung cancer cells and ovarian cancer‐associated macrophages could promote cancer cell growth through mechanisms such as the Wnt/beta‐catenin pathway and the oxidative phosphorylation pathway." (PMID 38633121, 2024).
lung cancer (18 papers, 2020 to 2025). A malignant neoplasm involving the lung. "Timd4 overexpression is also associated with increased lung cancer cell proliferation." (PMID 34517344, 2021). "In NSCLC, a comprehensive study documented the role of TIMD4 overexpression in the promotion of lung cancer cell proliferation and poor overall survival." (PMID 37256148, 2023). "Recent research has shown that TIMD4 is up‐regulated in tissues of oesophageal cancer, colorectal cancer, pancreatic cancer, breast cancer and lung cancer, and it can lead to poor prognosis in lung cancer patients by promoting the growth and proliferation of NSCLC cells." (PMID 40576208, 2025). "Recently, TIMD4 blockade has been proposed as a potential strategy to enhance the efficacy of CD8+ T cell‐based immunotherapies in cancers such as melanoma and lung cancer." (PMID 38633121, 2024). "As opposed to LIHC, TIMD4 is overexpressed in lung cancer and colorectal cancer, which is correlated with poor prognosis." (PMID 38683466, 2025). "TIMD4, a member of the TIM family of immunoregulatory proteins, is overexpressed in multiple tumor tissues, which has been proven to promote tumor cell growth and proliferation both in vitro and in vivo in lung cancer." (PMID 33816243, 2021).
Autoimmunity (11 papers, 2013 to 2024). The occurrence of an immune reaction against the organism's own cells or tissues. "Another study detected that mice deficient for TIMD4 or HAVCR1 have increased susceptibility for autoimmunity, as shown by hyperactive T- and B-cell responses in TIMD4−/− mice and increased Th2 responses in HAVCR1−/− mice." (PMID 29208769, 2018). "TIMD4 recognizes phosphatidylserine, which is essential to effectively eliminate apoptotic cells and prevent autoimmunity." (PMID 34476011, 2021). "Two differentially regulated transcripts (TIMD4, GADD45B) would promote inflammation or autoimmunity through involvement of cell death and survival pathways." (PMID 30308012, 2018). "Notably, Timd4-/- mice do not develop overt autoimmunity, likely due to the presence of other tolerance mechanisms, such as regulatory T cells and peripheral tolerance mechanisms." (PMID 31868579, 2019).
colorectal cancer (11 papers, 2020 to 2025). A primary or metastatic malignant neoplasm that affects the colon or rectum. "TIMD4 promoted the growth of colorectal cancer by activating angiogenesis and recruiting tumor-associated macrophages through the PI3K/AKT/mTOR signaling pathway." (PMID 34476011, 2021). "TIMD4 that was upregulated in all subtypes was observed to induce T cell exhaustion in cancer and promote colorectal cancer by activating angiogenesis and recruitment of tumor-associated macrophages." (PMID 34390367, 2021).
glioma (8 papers, 2020 to 2025). A benign or malignant brain and spinal cord tumor that arises from glial cells (astrocytes, oligodendrocytes, ependymal cells). "TIMD4 is a cell-surface glycoprotein and in cancers including renal cell carcinoma, diffuse large B-cell lymphoma, pancreatic cancer, and glioma, expression of TIMD4 has been associated with enhanced apoptosis, reduced clonogenic ability of cancer cells, and better survival." (PMID 37256148, 2023). "In fact, abnormal expression of TIMD4 has been reported in diverse cancer cells including diffuse large B‐cell lymphoma (DLBCL), non‐small‐cell lung cancer, glioma, renal cell carcinoma and histiocytic sarcoma and usually associated with adverse prognosis." (PMID 38633121, 2024).
atherosclerosis (6 papers, 2018 to 2023). A disease characterized by the build-up of fatty material and calcium deposition in the arterial wall resulting in partial or complete occlusion of the arterial lumen. "T‐cell immunoglobulin and mucin domain 4 (TIMD4) is a recognition receptor protein for efferocytosis that has been implicated in atherosclerosis mouse models." (PMID 37426678, 2023). "Previous studies have demonstrated that TIMD4‐mediated efferocytosis is closely associated with atherosclerosis." (PMID 37426678, 2023). "As a known immune checkpoint protein, TIMD4 plays an important role in the immune response of atherosclerosis." (PMID 37426678, 2023). "Intraperitoneal injection of a function blocking anti-Timd4 Ab effectively blocks efferocytosis in an atherosclerosis mouse model." (PMID 38127424, 2023). "Blockade of TIMD4 and HAVCR1 enhanced the risk of atherosclerosis in LDL receptor-deficient mice." (PMID 29208769, 2018). "In addition, the TIMD4-HAVCR1 rs12522248 SNP in our present study was associated with serum HDL-C level, which has a strong effect on the risk of atherosclerosis related diseases." (PMID 29208769, 2018). "The reduced phagocytic ability of macrophages due to the involvement of TIMD4 in efferocytosis may lead to the accumulation of inflammatory necrotic cells in advanced atherosclerosis, reducing the stability of plaque, leading to plaque rupture and some acute cardiovascular events." (PMID 37426678, 2023). "Therefore, whether we can also prepare a TIMD4 antibody to protect it from being cleaved by ADAM17 and promote the efferocytosis of macrophages to alleviate atherosclerosis, which will be our future research direction." (PMID 37426678, 2023).
non-small cell lung carcinoma (6 papers, 2020 to 2022). A group of at least three distinct histological types of lung cancer, including non-small cell squamous cell carcinoma, adenocarcinoma, and large cell carcinoma. "Some recent studies reported that TIMD4 had a correlation with some malignant carcinomas and its upregulation might lead to poor prognosis, as in diffuse large B-cell lymphoma and non-small-cell carcinoma." (PMID 32852285, 2020).
autoimmune disease (5 papers, 2015 to 2024). A disorder resulting from loss of function or tissue destruction of an organ or multiple organs, arising from humoral or cellular immune responses of the individual to their own tissue constituents. "Eleven proteins (increased: ATP5B, CALML5, COLEC11, FCGBP, PLEK, PLXND1; decreased: APOB, ATP8B1, FAM20C, LOXL3, TIMD4) were significantly altered in bvFTD with autoimmune disease compared to those without autoimmune disease." (PMID 34539672, 2021).
dyslipidemia (5 papers, 2015 to 2023). "Genome-wide association studies (GWAS) have identified genetic variants of TIMD4 (T cell immunoglobulin mucin protein 4) associated with dyslipidemia." (PMID 34290249, 2021). "GWAS identified genetic variants of Timd4 associated with dyslipidemia." (PMID 34290249, 2021). "Meta-analyses of the European ancestry genome-wide association study (GWAS) suggested that variants of rs3846663 in HMGCR, rs1501908 between TIMD4 and HAVCR1, rs2650000 near HNF1A, and rs6102059 near MAFB were associated with dyslipidemia." (PMID 37334397, 2023).
melanoma (5 papers, 2019 to 2025). A malignant, usually aggressive tumor composed of atypical, neoplastic melanocytes. "In melanoma pretreatment tumors, CD4+ T cells from nonresponders had significantly higher activation (for example, TIMD4/TIM3, OX40/EBI3, HLA) and cell cycle cGEP usage (P < 0.05 two-tailed t-test)." (PMID 40903640, 2025). "Activation and cell cycle cGEPs were elevated in pretreatment nonresponders of melanoma and NMSC (meta-analysis P < 0.05 for CellCycle-G2M, CellCycle-Late-S, TIMD4/TIM3, exhaustion, ICOS/CD38, OX40/EBI3 and HLA) and in the combined CRC cohort (P < 0.05 for all)." (PMID 40903640, 2025).
pancreatic cancer (5 papers, 2021 to 2025). "Consistent with previous studies, AXL and TIMD4 increased in patients with pancreatic cancer." (PMID 34778091, 2021).
viral infection (5 papers, 2019 to 2021). "HAVCR1 plays a critical role in regulating immune cell activity, particularly regarding the host response to viral infection, while TIMD4 is a T-cell immunoglobulin involved in regulating T-cell proliferation and lymphotoxin signalling." (PMID 32872585, 2020). "First, infection of TIM-4-sufficient pmacs is inhibited by addition of PS liposomes and, second, virus infection of pmacs from Timd-4-/- is markedly lower inTIM-4-sufficient pmacs." (PMID 31825972, 2019).
Stroke (4 papers, 2020 to 2025). Sudden impairment of blood flow to a part of the brain due to occlusion or rupture of an artery to the brain. "The other 4 proteins (APOE, PDE5A, METAP1D, and TIMD4) were associated with either dementia or stroke with consistent effects as the MR analysis." (PMID 39818967, 2025). "TIMD4 haplotypes have been reported to be associated with CAD and stroke as well as statin therapy in a case–control study performed in Chinese populations." (PMID 35595781, 2022).
gastric cancer (3 papers, 2018 to 2025). A primary or metastatic malignant neoplasm involving the stomach. "In this study, we used bioinformatic methods to identify FAM30A and TIMD4 as possible biomarkers for predicting gastric cancer metastasis." (PMID 34476011, 2021).
osteosarcoma (3 papers, 2013 to 2025). A usually aggressive malignant bone-forming mesenchymal neoplasm, predominantly affecting adolescents and young adults. "CD48, TIMD-4, B7-H6, CD134, B7-H5, CD47, and S100A8/A9 were significantly elevated in osteosarcoma patients, each linked to increased osteosarcoma risk." (PMID 40963634, 2025). "With the exception of B7-H2, all measured immune checkpoint proteins—CD48, TIMD-4, B7-H6, CD134, B7-H5, CD47, and S100A8/A9—were significantly elevated in osteosarcoma patients compared to healthy controls (p < 0.05)." (PMID 40963634, 2025).
renal cell carcinoma (3 papers, 2023 to 2025). "Taken together, these findings suggest that TIMD4 promotes the proliferation and migration of renal cell carcinoma cells, with a particularly significant effect on the ACHN cells, which are classified as renal papillary cell carcinoma." (PMID 40576208, 2025). "Results of in vivo experiments showed that silencing TIMD4 inhibits the proliferation of renal cell carcinoma." (PMID 40576208, 2025). "To investigate the impact of TIMD4 on the growth of renal cell carcinoma in vivo, we conducted animal experiments." (PMID 40576208, 2025). "To explore the regulatory role of TIMD4 in tumour cells, we confirmed its expression and function in renal cell carcinoma." (PMID 40576208, 2025). "Ultimately, we found that TIMD4 knockdown significantly decreased the migratory ability of the cells, indicating that TIMD4 promotes renal cell carcinoma invasion and metastasis by enhancing tumour cell migration." (PMID 40576208, 2025). "Overall, in tumour cells, TIMD4 acts as an oncogenic factor that promotes the progression of renal cell carcinoma and can serve as a novel anti‐cancer target to be used in combination with other anti‐cancer drugs to enhance their efficacy." (PMID 40576208, 2025). "Finally, experimental validation demonstrated that silencing TIMD4 can inhibit the proliferation and invasion of renal cell carcinoma cells." (PMID 40576208, 2025). "As for in vivo experiments, we discovered that silencing TIMD4 could significantly suppress the growth of renal cell carcinoma." (PMID 40576208, 2025). "Finally, both in vitro and in vivo experiments confirmed that silencing TIMD4 could effectively inhibit the proliferation and invasion of renal cell carcinoma." (PMID 40576208, 2025).
Cirrhosis (2 papers, 2020 to 2024). A chronic disorder of the liver in which liver tissue becomes scarred and is partially replaced by regenerative nodules and fibrotic tissue resulting in loss of liver function. "Furthermore, two distinct populations of MARCO+ KCs are distinguished by the expression of TIMD4, with a selective reduction in MARCO+ TIMD4− KCs observed in the livers of cirrhosis patients." (PMID 39328386, 2024).
coronary artery disease (2 papers, 2018 to 2023). "Little is known about the association of the TIMD4 (T-cell immunoglobulin and mucin domain 4 gene)-HAVCR1 (hepatitis A virus cellular receptor 1) variants and lipid metabolism, the risk of coronary heart disease (CHD) and ischemic stroke (IS)." (PMID 29208769, 2018).
dementia (2 papers, 2020 to 2025). Loss of intellectual abilities interfering with an individual's social and occupational functions. "The phenotypic transformation from homeostatic microglia towards reactive microglia in dementia pathologies is associated with TREM2, HLA-DRA, ENTPD1 (CD39), CD80 (B7-1), CD86 (B7-2), CCR5, CD274, ITGAX (CD11c), TIMD4 and MRC1." (PMID 33113879, 2020).
fatty liver disease (2 papers, 2020 to 2024). A reversible condition wherein large vacuoles of triglyceride fat accumulate in liver cells via the process of steatosis. "Research has shown that TIMD4 knockout mice exhibit exacerbated liver inflammation and hepatic steatosis compared to wild-type counterparts, although the exact mechanism remains unclear." (PMID 39497821, 2024).
hyperlipidemia (2 papers, 2018 to 2024). "Specifically, increased levels of GCKR (odds ratio [OR] = 0.42, 95% confidence interval [CI], 0.37–0.47; P = 3.64e-45) and TIMD4 (OR = 0.60, 95% CI, 0.50–0.72; P = 4.43e-08) decreased the risk of hyperlipidemia." (PMID 39474612, 2024).
calcific aortic valve disease (1 paper, 2025). "However, in calcific aortic valve disease (CAVD), only TIMD4 was up‐regulated, while in intracranial aneurysm (IA), only HAVCR2 showed increased expression." (PMID 40576208, 2025).
COVID-19 (1 paper, 2022). A disease caused by infection with severe acute respiratory syndrome coronavirus 2. "Both TIM-1 (HAVCR1) and its ligand TIM-4 (TIMD4) were upregulated in the plasma of severe COVID-19 patients." (PMID 35177642, 2022).
hepatocellular carcinoma (1 paper, 2023). A malignant tumor that arises from hepatocytes. "In support of this, intertumoral expression levels of KC signature genes, particularly TIMD4 and CLEC1B, were positively associated with the survival rates of hepatocellular carcinoma patients." (PMID 36821387, 2023).
infarction (1 paper, 2024). A localised pathological necrosis of tissue resulting from obstruction of the blood supply usually by a thrombus, an embolus, or vascular torsion. "Evidence to the contrary indicates that TIMD4 expression is sustained on resident Td+ macrophages up to 28 days subsequent to the infarction event, and it seems that the recruited macrophage cohort does not transition into TIMD4+ phenotype." (PMID 39223947, 2024).
leukaemia (1 paper, 2024). "Nonetheless, the molecular mechanisms underlying TIMD4 in leukaemias remain largely unknown." (PMID 38633121, 2024). "Although in each sample of Discovery Cohort at least half of the mononuclear cells were blasts (presumably leukaemia cells), we cannot be certain whether TIMD4 over‐expression occurred in the leukaemia cells or tumour‐associated myeloid cells." (PMID 38633121, 2024). "Fifth, our gene expression analyses were done on bulk populations of mononuclear cells isolated from bone marrow samples, and we do not know whether TIMD4 over‐expression occurred in the leukaemia cells or other cells in the bone marrow." (PMID 38633121, 2024).
lung adenocarcinoma (1 paper, 2021). A carcinoma that arises from the lung and is characterized by the presence of malignant glandular epithelial cells. "In human lung adenocarcinomas a combined cDC1/Timd4 gene signature predicts survival in early stages patients, and responses to PD-1 treatment in a cohort of lung adenocarcinoma patients." (PMID 33854047, 2021).
lupus-like syndromes (1 paper, 2022). "Loss of function of complement component 1q (C1q), T cell immunoglobulin and mucin domain-containing 4 (TIM4), and milk fat globule-EGF factor 8 (MFG-E8) result in lupus-like syndromes in humans and in mice." (PMID 35192551, 2022).
oligospermia (1 paper, 2017). Decreased number of spermatozoa in the semen. "Eight genes among 817 genes (0.01%) (ADAM32, DYNLRB2, KLHL10, RIMBP3C, SEPT12, TIMD4, TSACC and TTC25) were common between MArrest and teratospermia, and three genes among 435 genes (0.007%) (HRASLS, LIMS3 and MRPL42) were common between oligospermia and teratospermia." (PMID 29150651, 2017).